INS (insulin)
Diseases named in the same sentence as INS in open-access papers (continued):
Sharing a sentence is not in itself a finding about the gene and the disease.
diabetes (continued). "One patient suffered from diabetes as concomitant disease and reported a decreased (75% of initial units) insulin requirement during the study." (PMID 21794124, 2011). "Since Akt isoforms are key downstream kinases of the insulin signaling cascade and crucial elements in retinal cell survival, we also analyzed their activity in response to diabetes and both treatments." (PMID 22046295, 2011). "Although human insulin has contributed much in clinical treatment of diabetes for a long time, there are still some difficulties and challenges of hypoglycemia and short half-life." (PMID 22187651, 2011). "Insulin fibrillation studies attain significant importance considering the prevalence of diabetes and the requirement of functional insulin in each dose." (PMID 22132167, 2011). "Diabetes as the “sugar” disease has been identified for centuries, but it has been shown that insulin has numerous neurotrophic, metabolic and endocrine functions in the brain, being centrally involved in memory and neuronal survival." (PMID 22654727, 2011). "Replacement of insulin production by pancreatic islet transplantation has great potential as a therapy for type 1 diabetes mellitus." (PMID 22013504, 2011). "In the NOD mouse, injection of insulin-specific T-cell clones accelerates diabetes and protection is obtained by injecting insulin in incomplete Freund's adjuvant in prediabetic mice." (PMID 21785617, 2011). "In the treatment groups, both Rutin and Naringin in combination with insulin treatment in diabetic rats produced protection from diabetes and improved all the sperm parameters, decreased the MDA levels and increased the SOD and catalase levels." (PMID 24250392, 2011). "The unique properties of L-cells and the GLP-1 promoter provide a strong rationale to use the GLP-1 promoter to express glucose-regulated insulin in intestinal L-cells for the potential treatment of diabetes." (PMID 22047106, 2011). "Most of the patients had had diabetes for quite a long time and were relieved to get off insulin and have the chance to lose weight." (PMID 22196251, 2011). "Elevated levels of free fatty acid have been inhibiting insulin secretion by mitochondrial oxidation in the establishment of insulin resistance in diabetes mellitus." (PMID 21716679, 2011). "So-called insulin-induced lipoatrophy is a rare, albeit feared condition mostly in patients with type-1 diabetes mellitus." (PMID 22145998, 2011). "Known association of the gene with a function central to disease pathogenesis (for example, insulin secretion for diabetes)." (PMID 21291537, 2011). "Elevations in FFA promote metabolic disturbances by impairing the ability of cells to store glucose as glycogen and to respond to insulin, which cumulatively are capable of promoting the development of diabetes." (PMID 21569551, 2011). "Further analysis demonstrated that both normalization of hyperglycemia and increased ocular insulin signaling reversed diabetes-induced insulin receptor/Akt signaling defects." (PMID 22046295, 2011). "In those times, there was a quest for metabolically superactive insulins, i.e. "tailor-made" insulin derivatives with enhanced biopotency, like the insulin derivative B10Asp, to make the treatment of diabetes mellitus more efficacious." (PMID 21714872, 2011). "Combining received knowledge with one's own knowledge and experiences of living with diabetes, obtained from a trial and error approach, yields greater understanding, as the person learns how diabetes, insulin and one's body interact." (PMID 21878104, 2011). "Certain properties of enteroendocrine cells, including glucose sensitivity, insulin processing capability and a regulated secretion pathway, make them ideal potential candidate cells for diabetes gene therapy." (PMID 22047106, 2011).
diabetes (continued). "HSPGs expression was evaluated in skeletal muscle, because it is the major organ responsible for glucose uptake under insulin-stimulated conditions and it is affected by the metabolic deregulation observed in diabetes." (PMID 21518435, 2011). "Cinnamon is used in traditional medicine for treating diabetes and it was found to have insulin secretagogue property and insulin sensitizing property." (PMID 21711570, 2011). "But here in our current study, the type 2 diabetes patients with a higher HbA1C, fasting glucose and a longer duration of diabetes are likely to be accompanied by worsening function of beta cells to secrete adequate amounts of insulin." (PMID 21816063, 2011). "STZ-induced diabetic animals showed stable signs of diabetes, including hyperglycemia, reduced levels of insulin." (PMID 22054019, 2011). "Women diagnosed with diabetes prior to pregnancy (pre-existing diabetes) will experience an increase in insulin demands during pregnancy." (PMID 21501437, 2011). "Other factors known to affect inflammatory markers (gender, duration of diabetes or treatment, lipid-altering and anti-hypertensive medications) were similar in both insulin treatment groups." (PMID 21517955, 2011). "It has been recently suggested that ER stress plays a central role in the development of insulin resistance and diabetes by impairing insulin signaling through c-Jun NH2-terminal kinase (JNK) activation." (PMID 21375727, 2011). "Support for a direct role of insulin in bone comes mainly from animal studies, specifically rats, where streptozocin-induced diabetes led to defects of bone mineralization." (PMID 21772974, 2011). "This review addresses its potential, when used at typical doses, to affect glucose metabolism and insulin sensitivity in healthy individuals and those with diabetes or ‘pre-diabetes’." (PMID 21218504, 2011). "A mean follow-up of about two years showed significant improvements of all clinical parameters related to diabetes (a decrease in insulin requirements, an increase in C-peptide levels, and absence of diabetic ketoacidosis)." (PMID 22007286, 2011). "Glycemic control is fundamental to management of diabetes, and medical treatment with metformin and insulin regulating the glucose level have been found to improve endothelial function in diabetic subjects." (PMID 26859486, 2011). "Insulin fibril formation has also been a limiting factor in long-term storage of insulin for treatment of diabetes." (PMID 21819598, 2011). "We report a case of severe localised lipoatrophy developing during insulin pump-treatment (continuous subcutaneous insulin infusion) with the insulin analogue lispro (Humalog®) in a woman with type-1 diabetes mellitus." (PMID 22145998, 2011). "Type 2 diabetes mellitus is a progressive disorder, with many patients eventually requiring insulin therapy." (PMID 21542916, 2011). "Diabetes has been recognized for millennia's and is characterized by persistent hyperglycaemia due to defects in either insulin secretion, insulin action, or a combination." (PMID 21829666, 2011). "Diagonosis of diabetes made by a medical practitioner, or patient using hypoglycemic medication,either oral or insulin or both medication, either oral or insulin or both." (PMID 21435202, 2011). "Increased incidence of diabetes has been described after increased insulin production and vice versa, and actual hyperinsulinemia has been observed in relation to the diabetogenesis." (PMID 21143521, 2011). "Diabetes mellitus is a metabolic disorder characterized by hyperglycemia due to defect in insulin secretion, action, or both." (PMID 20924498, 2011). "In accordance with the lower prevalence of diabetes, offspring had lower glucose levels (P<0.001) and lower levels of insulin (P=0.006)." (PMID 21191145, 2011). "We and others have shown that diabetes depresses retinal insulin signaling with decreased kinase activities of the insulin receptor and downstream signaling proteins including Akt1 and Akt3." (PMID 22046295, 2011).
diabetes (continued). "The AD brain exhibits regional glucose hypometabolism as well as abnormalities in insulin signaling, both components of diabetes mellitus." (PMID 22332001, 2011). "The final logistic model for presence of obesity included age, sex, diastolic blood pressure, diabetes, homocysteine, insulin resistance, apoA1, and apoB." (PMID 21159217, 2011). "An important element in characterizing retinal transcriptomic changes with diabetes that are unresponsive to insulin treatment is determining when these diabetes-induced changes first occur." (PMID 21575160, 2011). "Subgroups of patients with type 2 diabetes mellitus demand large insulin doses to maintain euglycemia." (PMID 22114711, 2011). "These are all theories, and more studies are needed to assess the effect of insulin on bone in male patients with diabetes." (PMID 21772974, 2011). "As various staff members commented, the greater the RN's diabetes clinical experience the more likely they were to have deviated from TMS recommended insulin doses during the trial." (PMID 21542916, 2011). "In this work, we demonstrate for the first time that targeted disruption of the Dicer1 gene specifically in β-cells leads to progressive reduction in insulin secretion, glucose tolerance and development of diabetes." (PMID 22216196, 2011). "Fourth, disease and treatment kinetics are quite different, as NOD mice are most commonly treated for preventing diabetes at an early stage, before the appearance of any circulating autoimmune marker such as anti-insulin aAbs (IAA)." (PMID 21647401, 2011). "To date, the dysfunction of glucagon secretion in diabetes is vaguely considered to result from defective glucose sensing and insulin resistance in liver and muscle." (PMID 21283589, 2011). "Future therapies for both type I and II diabetes rely on renewable sources of functional insulin-producing β-cells." (PMID 21909240, 2011). "While insulin clearly normalizes the majority of genes dysregulated in response to diabetes, a number of genes related to inflammatory processes, microvascular integrity, and neuronal function are still altered in expression in euglycemic diabetic rats." (PMID 21575160, 2011). "The significance of insulin used in the treatment of diabetes drew enormous interest in this hormone and scientists have been studying the mechanisms of insulin signaling proteins to understand how the cascading works at cellular level." (PMID 21364910, 2011). "After developing diabetes, mice were kept alive by subcutaneous administration of insulin pellets for 2-4 weeks to stabilize their glycemic levels prior to implantation of neonatal NOD.scid pancreas under their kidney capsule." (PMID 21722394, 2011). "A challenging approach to generating surrogate β-cells for cell replacement therapy in diabetes is the direct reprogramming of liver cells into insulin-producing cells." (PMID 21876779, 2011). "In a recent study, the property of matured insulin to unfold and oligomerize has been harnessed to achieve a glucose regulatory effort for treatment of diabetes in rodent models." (PMID 21559376, 2011). "We have already reported this interesting feature of STZ-induced diabetes in female rats at the age of 14 months when about 30% of animals displayed regeneration of the insulin-secreting tissue." (PMID 21792353, 2011). "Glucose levels are measured intraoperatively if the patient has diabetes or has been administered any insulin preoperatively." (PMID 21912542, 2011). "Diabetes mellitus is a metabolic disease characterized by hyperglycemia resulting from defects in insulin secretion, insulin action or both." (PMID 19887507, 2011). "Thiazolidinediones (TZDs) are synthetic PPARγ (peroxisome proliferator-activated receptor gamma) agonists and a class of drugs for diabetes mellitus type 2 that can decrease blood sugar efficiently by enhancing insulin sensitivity." (PMID 22135675, 2011).
diabetes (continued). "Insulin deficiency is the prime basis of all diabetic manifestations and agents that can bring about insulin secretion would be of pivotal significance for cure of diabetes." (PMID 22169757, 2011). "During the course of insulin resistance several inflammatory cytokines and lipid metabolites like free fatty acids interrupt with the normal insulin signaling and promote type 2 diabetes mellitus." (PMID 22008087, 2011). "Diabetes is characterized by consistently elevated blood glucose levels, decreased insulin levels and increased heart/body weight ratio indicative of hypertrophied heart was observed in the STZ diabetic rat." (PMID 22054019, 2011). "Since then, insulin treatment and technologies for insulin delivery have improved and international guidelines for managing diabetes among children and adolescents have been established." (PMID 22185481, 2011). "One study into the cost of caring for children with T1DM in Sudan found that the mean annual expenditure on diabetes care was US$283 per diabetic child, 36% of which was spent on insulin." (PMID 21756350, 2011). "The curriculum covers all aspects of living with diabetes but places a strong emphasis on blood glucose testing, carbohydrate counting and matching quick-acting insulin to this." (PMID 21878104, 2011). "Despite the important implications for diabetes control in insulin-injecting patients, there is a dearth of information in children about the subject." (PMID 21838879, 2011). "Insulin discovery in the early 1920s transformed diabetes from a uniformly fatal condition into a disease requiring life-long insulin-replacement therapy." (PMID 22071283, 2011). "This work predicted the involvement of about 20 enriched pathways, some of which are very commonly involved in diabetes and/or obesity like the insulin signaling, PPAR signaling, Adipocytokine signaling, MAPK signaling, Jak-STAT signaling pathways." (PMID 20942928, 2010). "In our sample, responders were younger and more often male, more frequently treated with insulin or with several OHAs than with a single OHAs, less frequently treated for a cardiovascular disease and received an overall better quality of diabetes care." (PMID 21044345, 2010). "Overall, costs increased with age, diabetes duration and were higher for patients treated with insulin compared to those treated with oral hypoglycemic agents or with diet control only." (PMID 21059202, 2010). "Most early studies on self-assessed health among the diabetic population have focused on diabetes-specific attributes, such as the duration of diabetes, diabetes complications, and the use of insulin." (PMID 20500890, 2010). "Inherited variations have been identified from studies of monogenic diabetes, and have provided insights into β cell physiology, insulin release, and the action of insulin on target cells." (PMID 20174558, 2010). "A 33-year-old Caucasian woman with insulin-treated diabetes presented with continuous epigastric pain of four hours duration." (PMID 20420664, 2010). "Regarding glucoregulatory health, CR has been shown to decrease fasting glucose and insulin levels, increase insulin sensitivity, decrease body fat percentage, and lower the incidence of diabetes." (PMID 21092212, 2010). "The process analysis accompanying the subsequent evaluation will explore implementation issues and compare the experience of managing diabetes and insulin management and self-care processes between the intervention and control pathways." (PMID 20875112, 2010). "The FLI includes: BMI, waist circumference, triglycerides and gamma glutamyl transferase, and the NAFLD-FLS: the metabolic syndrome, diabetes, insulin, alanine aminotransferase, and asparate aminotransferase." (PMID 20529259, 2010). "The development of type 2 diabetes mellitus is induced by the decreased insulin sensitivity, which leads to increased insulin production." (PMID 21274322, 2010).
diabetes (continued). "Insulin regulation of vascular NKA gene expression has been reported as an important factor in the development of hypertension in diabetes." (PMID 22457695, 2010). "In patients with diabetes for more than five years, 11% (33 of 296) of adults, compared with 0 of 75 adolescents, retained substantial insulin secretory capacity." (PMID 27713291, 2010). "Diabetes is a progressive disease characterized by hyperglycemia, resulting from defects in insulin secretion, its function, or both." (PMID 20462406, 2010). "Streptozotocin (STZ), a β-cytotoxin, induces ‘chemical diabetes’ in a wide variety of animal species including rat by selectively damaging the insulin-secreting β-cells of the pancreas." (PMID 20431798, 2010). "During the next 7 years, prostate cancer, rectal ulcer necessitating colon diversion, hemolytic anemia, thrombocytopenia, myelodysplastic syndrome, and diabetes mellitus developed in the patient; he was treated with insulin for the diabetes." (PMID 20409382, 2010). "Hyperglycemia develops between 8 and 10 weeks of age, leading to overt diabetes and collapsing insulin secretion." (PMID 20652060, 2010). "This difference is due to the fact that uncontrolled diabetes is lethal in the DR-BB model and the animals were provided an insulin pump or injected with insulin daily after each became diabetic." (PMID 20122173, 2010). "During the ICU stay, more patients with a history of insulin-treated diabetes developed renal failure and underwent hemodialysis than did those without a history of insulin-treated diabetes." (PMID 20132545, 2010). "Insulin is the longest-standing and most effective treatment for diabetes, because it is able to reduce glycosylated hemoglobin (HbA1c) to normal levels." (PMID 20718958, 2010). "Conversely, an impaired response of Akt to stimulating factors like insulin in peripheral tissues contributes to metabolic syndromes and diabetes mellitus." (PMID 20585550, 2010). "Inter-item agreement was acceptable for the ITQ scales from the initial administration for type 1 and type 2 participants (alphas = .71/.68 for Diabetes Worries.85/.84 for Perceptions of Insulin Therapy.83/.81 for Treatment Satisfaction)." (PMID 20334647, 2010). "In combination with the in vivo and molecular changes found in RV glucose metabolism and insulin signaling, this suggests that diabetes affects both ventricles." (PMID 20550678, 2010). "There is great interest in the contributions of ER stress in beta cells to the pathogenesis of diabetes and the failure of transplanted human islets to maintain insulin secretion." (PMID 20585452, 2010). "Of the 3147 patients included in the SOAP study, 226 (7.2%) had previously diagnosed insulin-treated diabetes mellitus." (PMID 20132545, 2010). "In fact, diets with a low charge of carbohydrates were used for the treatment of diabetes before insulin or other medication therapies were available." (PMID 21143928, 2010). "These mutations account for a significant subset of cases of permanent neonatal-onset diabetes mellitus, a syndrome referred to as Mutant INS-gene induced Diabetes of Youth (MIDY)." (PMID 20948967, 2010). "The aim of this study was to investigate how patients’ expectations about and experiences with insulin therapy contribute to diabetes treatment satisfaction." (PMID 20370840, 2010). "For optimal glycemic control during pregnancy in women with pre-existing diabetes, intensified insulin regimens with multiple doses of subcutaneous long and short-acting insulins or continuous insulin infusion, usually give the best results." (PMID 20416099, 2010). "Preceding the onset of diabetes, glucose intolerance with impaired insulin secretion and impaired lipid catabolism are also observed." (PMID 20508774, 2010). "Further study is needed to explore the underlying obstacles to engaging in leisure time physical activity among diabetes who use insulin." (PMID 20500890, 2010).